IL6 (interleukin 6)
Diseases named in the same sentence as IL6 in open-access papers (continued):
Sharing a sentence is not in itself a finding about the gene and the disease.
cardiac hypertrophy (continued). "IL6 is also correlated to IMT, because the IL6 over expression induces cardiac cellular growth and cardiac hypertrophy." (PMID 30246793, 2018). "Previous study indicated that IL6-related pathways play a crucial role in eccentric cardiac hypertrophy, including IL6-related MEK5-ERK5 signaling and JAK2-STAT3 signaling." (PMID 28479925, 2017). "Either an AT1 blocker or angiotensin-converting enzyme inhibitor prevented development of cardiac hypertrophy and fibrosis, systolic dysfunction and increased IL-6 expression in transgenic mice." (PMID 28771545, 2017). "These previous observations suggest that IL-6 is a downstream effector of Ang II signaling to mediate cardiac hypertrophy." (PMID 28771545, 2017). "IL-6 has a hypertrophic activity for cardiomyocytes both in vitro and in vivo, and is involved in exogenous Ang II-induced cardiac hypertrophy." (PMID 28771545, 2017). "Genetic deletion of IL-6 was recently reported to attenuate pressure overload-induced cardiac hypertrophy." (PMID 27899891, 2016). "IL-6 appears to be an important mediator in ventricular hypertrophy and does increase nitric oxide production." (PMID 27884156, 2016). "The RT protocol was able to attenuate cardiac hypertrophy, left ventricular collagen volume fraction and reduced IL-6 and the ratio of TNF-α/IL-10; also, there was increased IL-10 in CHF rats." (PMID 25340545, 2014). "Both IL-6 production and cardiac hypertrophy have notable links to the prevalence of cardiovascular events and morbidity." (PMID 25505598, 2014). "Comparable hypertensive responses to angiotensin II infusion were noted in both genotypes, but hypertensive TRPA1 KO mice showed blunted production of IL-6 and increased cardiac hypertrophy compared to WT mice." (PMID 25505598, 2014). "Activated NF-κB, in turn, induces transcription of the interleukin-6 gene (IL-6) ensuing the stimulation of IL-6-mediated pathways involved with foetal gene expression and cardiac hypertrophy." (PMID 25216213, 2014). "TRPA1 KO mice presented with more substantial cardiac hypertrophy, but blunted ability to increase IL-6 production; results which are difficult to reconcile." (PMID 25505598, 2014). "Previously, it was reported that interleukin-6 (IL-6) stimulates cardiomyocytes via the gp130 receptor and leads to cardiac hypertrophy and cardiac dysfunction." (PMID 23372656, 2013). "Chronic hypertension causes cardiac hypertrophy, characterized by low-grade inflammation and accompanied by increased expression and activity of TLR4, and elevated gene expression of TNF-α and IL-6 in cardiac tissue." (PMID 24223475, 2013). "IL-6 has previously been found toplay a role in cardiac hypertrophy through the activation of the JAK-STAT pathway." (PMID 23874609, 2013). "Plasma cytokine levels, such as IL-6 and sTNF-R1, were correlated with left ventricular mass index, but when a logistic regression was performed to predict hypertrophy, only sTNF-R1 was independent predictor." (PMID 22384001, 2012). "IL-6 can be expressed in myocardium under various forms of stress and, also, it has the ability to induce apoptosis, cardiac hypertrophy and fibrosis in myocardium." (PMID 21453457, 2011). "Overexpressed IL-6 in the myocardium as a result of AMI appears to play a central role in pathogenesis of cardiac hypertrophy." (PMID 21792366, 2011). "Cardiomyocyte development through IGF, and cardiac hypertrophy mediated by the IL6 signaling axis are represented herein by single components belonging to their respective pathways." (PMID 18184438, 2008). "In mouse experiments, S1PR1 expression is upregulated during myocardial hypertrophy and can lead to myocardial hypertrophy and fibrosis by inducing interleukin (IL)-6 secretion in a manner dependent on Ang II-AT1, though this occurs only in proliferating fibroblasts and not in cardiac myocytes." (PMID 38015241, 2024).
cardiac hypertrophy (continued). "However, D-gal-induced cardiac hypertrophy, myocardial IL-1β and IL-6 levels, and β-gal-positive cells were significantly reduced by the overexpression of miR-30a-5p." (PMID 39511427, 2024). "Furthermore, TP53INP1 silencing considerably alleviated D-gal-induced cardiac hypertrophy, myocardial IL-1β and IL-6 levels, and β-gal-positive cells in the KO mice." (PMID 39511427, 2024). "Previous studies have suggested that IL-6 plays an important role in cardiac hypertrophy." (PMID 37047522, 2023). "Furthermore, persistence elevated IL-6 concentrations can lead to cardiac hypertrophy mainly through IL-6 trans-signaling." (PMID 37996879, 2023). "Changes in inflammatory markers (such as C-reactive protein (CRP), interleukin-6 (IL-6), and tumor necrosis factor-α (TNF-α)) are associated with long sleep duration, which may contribute to ventricular hypertrophy." (PMID 38131034, 2023). "Finally, we explored the effect of Cad-11 on cardiac myocyte hypertrophy as well as its involvement in IL-6 signaling." (PMID 37047522, 2023). "Chronic elevation of IL-6 induces myocardial hypertrophy and decreases contractility." (PMID 37887854, 2023). "The determination of protein expressio for IL6 in cell supernatant by ELISA was also increased in the model of cardiac hypertrophy, and was significantly inhibited by hirudin treatment, while the phosphorylation of STAT3 and MAPK1 was also significantly inhibited." (PMID 35784743, 2022). "In addition, C/EBPδ protein levels can be induced by IL-6 and mediated by STAT3 in cardiomyocytes, leading to cardiac hypertrophy which can cause cardiac fibrosis through multiple mechanisms." (PMID 36299447, 2022). "Double-transgenic mice overexpressing human IL-6 and soluble IL-6R showed no myocardial phenotype at the age of two months but developed cardiac hypertrophy at five months of age, suggesting that cardiac remodeling requires chronic exposure to IL-6/IL-6R signaling." (PMID 35163735, 2022). "Gbotosho and colleagues administered plasma heme in Townes sickle cell mice that resulted in increased IL-6 levels and increased gene expression of cardiac hypertrophy, consistent with the notion that increased hemolysis in sickle cell disease leads to an inflammatory-mediated vasculopathy." (PMID 35563154, 2022). "Many studies over the last two decades have shown that IL-1β, IL-6, and TNF-α are intimately linked to cardiac fibrosis, pathological cardiac remodeling, and cardiac hypertrophy, and the inflammatory cytokines induced following the activation of the nuclear factor-κB (NF-κB) pathway." (PMID 36164390, 2022). "Additionally, the upregulation of NF-κB—together with the excessive expression of pro-inflammatory cytokines such as interleukin-6 (IL-6) and tumor necrosis factor-alpha (TNF-α)—associated with cardiac hypertrophy has been observed in L-NAME hypertensive rats." (PMID 33801631, 2021). "Stimulation of isolated cardiomyocytes with IL-6 and soluble IL-6R could induce hypertrophy, whereas IL-6 inhibition reduced cardiac hypertrophy and fibrosis in angiotensin II-treated mice." (PMID 34276413, 2021). "A study using the animal model suggested that elevated production of IL-6 induced by aldosterone could further promote collagen production and cardiac hypertrophy via the IL-6 trans-signaling pathway." (PMID 34485413, 2021). "Of further interest, signal transducer and activator of transcription 3 (STAT3) may be important for interleukin 6-mediated cardiac hypertrophy, which we showed both to be downregulated by baicalein and BHCl." (PMID 33668293, 2021). "MiR-320 mimics accelerated cardiac hypertrophy and cardiac fibrosis via the IL6/STAT3/PTEN axis." (PMID 34582362, 2021). "In addition, IL-6 activates the JAK2/STAT3 signaling pathway in cardiac hypertrophy, and it is produced by macrophages and cardiomyocytes in response to hypertrophic stimulus." (PMID 34194329, 2021).
cardiac hypertrophy (continued). "However, IL-6's role in cardiac hypertrophy induced by pressure overload remains controversial, possibly due to differences in the severity of TAC and in follow-up durations." (PMID 33324685, 2020). "With elevated cardiac PlGF at baseline in SCD mice and further inducibility by heme, cardiac hypertrophy may develop via IL-6 signaling." (PMID 33584641, 2020). "Furthermore, administration of extracellular heme further increased IL-6 and cardiac hypertrophy genes expression." (PMID 32973791, 2020). "Moreover, severe injury such as cardiac hypertrophy is displayed, which indicates the involvement of several DRGs of IL6, LUM, LRG1, PLG, with other molecules such as Alpha actinin, PDGF, Tgf beta, and TLR2 and TLR4." (PMID 32753925, 2020). "Therefore, it can be envisaged that prolonged hemolysis induced PlGF and IL-6 in SCD feeds the vicious cycle of inflammation via an autocrine feedback system resulting in reactivation of genetic cardiac hypertrophy program." (PMID 33584641, 2020). "In addition, these cytokines are also involved in mediating cardiac remodeling as evidenced by the finding that genetic deletion of the TNF-α gene leads to a reduction in TAC-induced hypertrophy, whereas infusion of IL-6 in rat induces cardiac hypertrophy." (PMID 33192505, 2020). "Moreover, Akt activation promotes TNF-α-induced elevation in mRNA levels of IL-6, IL-1α, and IL-1β in cardiac fibroblasts and cardiac hypertrophy in primary cardiomyocytes." (PMID 32831633, 2020). "Because our data showed upregulation of cardiac hypertrophy genes following heme treatment in SS mice, there is a possibility that heme is inducing IL-6 in the heart and prolonged activation and exposure to IL-6 could contribute to LVH in SCD patients." (PMID 33584641, 2020). "Our results align with published evidence from rodents and humans without SCD that suggest a causal relationship between IL-6 and cardiac hypertrophy." (PMID 32973791, 2020). "Interestingly, transplantation of JAK2V617F-harboring hematopoietic stem cells into mice accelerated cardiac hypertrophy and fibrosis, which were accompanied by a large number of infiltrating macrophages and elevated IL-6 expression in the heart." (PMID 33628203, 2020). "Further studies in murine cardiac hypertrophy models using animals with cardiac fibroblast-specific deletion of the IL6 gene would be useful to confirm this hypothesis." (PMID 31394846, 2019). "Moreover, IL-6 has also been incriminated in the pathogenesis of cardiac hypertrophy and dysfunction, through the activation of the Ca2+/calmodulin-dependent protein kinase II and STAT3 pathways." (PMID 30177883, 2018). "We found in the transgenic (TG) mice that augmented S1PR1 signaling in myofibroblasts led to the development of pathological cardiac hypertrophy with interstitial fibrosis, which was mediated through the paracrine actions of Ang II and interleukin-6 (IL-6) released by myofibroblasts." (PMID 28771545, 2017). "Although the effect of IL-1β on angiotensin II-dependent cardiac hypertrophy is unknown, data from clinical settings and experiments have indicated that IL-22-IL-22R1-IL-10R2 binding can regulate IL-6, IL-17, IL-1β, TNF-α, and IFN-γ expression." (PMID 29358851, 2017). "Despite the lack of effect of IL-6 on arterial pressure, IL-6 is associated with a significant degree of cardiac fibrosis and hypertrophy, suggesting that IL-6 can produce cardiac alterations independent of changes in arterial pressure." (PMID 29186034, 2017). "Finally, we tested the effects of administration of a specific IL-6 neutralizing antibody on cardiac hypertrophy and STAT3 phosphorylation in TG mice." (PMID 28771545, 2017). "In a rat model of cardiac hypertrophy by artery ligation, collagen synthesis and hypertrophy occur but inhibition of IL-6 resulted in blockade of fibrosis and hypertrophy suggesting that IL-6-mediated collagen synthesis is driving the fibrosis and hypertrophy through a direct mechanism." (PMID 28194150, 2016).
cardiac hypertrophy (continued). "The beta values for IL-18 and IL-6 were equivalent, whereas considering the critical roles of IL-18 in heart diseases and cardiac hypertrophy, IL-18 may represent a better biomarker that can reflect the development of FC in patients with IVS4+919 G>A mutation." (PMID 27888626, 2016). "Also it was demonstrated that 5-HT2BR is essential for isoproterenol-induced cardiac hypertrophy, which is regulated by interleukin-6 (IL-6), interleukin-1β (IL-1β), and tumor necrosis factor α (TNFα) cytokine production by cardiac fibroblasts." (PMID 25667920, 2015). "Consistent with this hypothesis, Hirota and coworkers demonstrated a concomitant overexpression of both IL-6 and IL-6 receptor in a mouse model of cardiac hypertrophy." (PMID 23365487, 2013). "Elevated IL-6 mRNA is observed in patients of cardiac hypertrophy with hypertrophic cardiomyopathy." (PMID 21785627, 2011). "Besides, Ang II activates STAT3, which interacts with TLR4 and increases IL-6, and, in turn, promotes the second STAT3 activation, leading to an upregulated expression of genes for cardiac hypertrophy through the IL-6/glycoprotein 130 (gp130)/Janus-family tyrosine kinases 2 (JAK2) pathway." (PMID 37113698, 2023). "Further research confirmed that RORα function deficiency elevated interleukin 6 (IL-6) expression, promoted STAT3 activation, deteriorated mitochondrial function, aggravated oxidative stress, decreased total cardiomyocyte number, and finally exacerbated Ang II-induced myocardial hypertrophy." (PMID 36834872, 2023). "In addition, acute pressure overload and mechanical stress can activate JAK1, JAK2, TYK2, STAT2, STAT3, and the IL-6 family (including cardiotrophin 1, LIF, and IL-6 itself), and it has been suggested that this activation is a potentially important mechanism of myocardial hypertrophy." (PMID 36671504, 2023). "Thus, it was found that the gene expression of IL-6, a pro-inflammatory molecule known to be involved in the cardiac hypertrophy, was significantly increased in hiPSC-CMs stimulated with AngII and TGF-β1 for 48 h compared to unstimulated cardiomyocytes in the control position (1.81-fold, *p < 0.05)." (PMID 36299891, 2022). "A mouse experiment shows that the expression of S1P1 is upregulated during myocardial hypertrophy and could be overexpressed in interleukin (IL)-6 secretion depending on the Ang II-AT1, causing cardiac hypertrophy and fibrosis, and affecting the systolic function of the heart." (PMID 30687087, 2018). "However, IL-6 activates other signaling pathways that might contribute to cardiac hypertrophy, including several that affect calcium handling, a proven protagonist of cardiac myocyte hypertrophic growth." (PMID 27899891, 2016). "In addition, resistance training was able to reduce myocardial hypertrophy (P<0.05), left ventricular total collagen volume fraction (P<0.01), IL-6 (P<0.05), and TNF-α/IL-10 ratio (P<0.05), as well as increasing IL-10 (P<0.05) in chronic heart failure rats when compared to the S-CHF group." (PMID 25340545, 2014). "On the other hand, IL-6 levels might also be involved in the determinism of cardiac hypertrophy." (PMID 23365487, 2013). "Chronic activation of JAK/STAT3 can induce cardiac hypertrophy, as evidenced by Ang II-induced activation of TLR4 and STAT3, promoting hypertrophy via the IL-6/JAK2/STAT3 pathway." (PMID 38495094, 2024). "The LAM1-specific pathways included IL-1 and IL-6 signaling, whereas LAM2-specific populations consisted of neuronal-, inflammatory-, cardiac-hypertrophy-, and growth-factor-related pathways." (PMID 38776872, 2024). "In this report, we demonstrated the role of IL-6 in ERK/JNK activation in cardiac fibrosis and hypertrophy." (PMID 37047522, 2023). "To further characterize cardiac hypertrophy and inflammation, we determined ventricular levels of ANP and IL6 as markers for these conditions, respectively." (PMID 38169715, 2023).
cardiac hypertrophy (continued). "AngII, renowned for its instrumental role in fostering cardiac hypertrophy through the renin-angiotensin-aldosterone (RAA) system, stimulates the production of IL-6." (PMID 37637634, 2023). "The expression and activation of pro-inflammatory cytokines, such as IL-1β, IL-6, IL-8, and TNF-α are involved in myocardial fibrosis, myocardial hypertrophy, oxidative stress-related injury, and cardiac dysfunction." (PMID 34997266, 2022). "It is well known that the level of ANP indicates changes in cardiac hypertrophy, and the levels of TNF-α, IL-6 and fibrin indicate myocardial inflammation and fibrosis induced by cardiac hypertrophy." (PMID 35249458, 2022). "The release of inflammatory cytokines such as TNF-α, IL-1β, IL-6, and IL-8, and the production of inducible nitric oxide synthase (iNOS) and cyclooxygenase-2 (COX-2), can lead to cardiac hypertrophy and impaired cardiac function." (PMID 35276939, 2022). "AngII-induced myocardial hypertrophy in WT mice with increased serum CK, LDH, IL-6, and TNF-α levels compared with the control group." (PMID 36046685, 2022). "The JAK/STAT pathway also transduces signals for a wide array of cytokines and growth factors including ANGII, TNF-α, IL-1β, IL-6 and IFN-γ, all of which have been involved in cardiac hypertrophy." (PMID 34225646, 2021). "In the ISO-induced cardiac hypertrophy rat model, COX-2 was highly expressed, accompanied by elevation of cardiac NF-κB, TNF-α, and IL-6." (PMID 32848764, 2020). "In our study, all biomarkers with the exception of IL-6 correlated with functional class (NYHA functional class), renal function (GFR) or cardiac hypertrophy (LVH or IVM)." (PMID 30996283, 2019). "In mammals, the JAK/STAT pathway transduces signals for a wide array of cytokines and growth factors including AngII, TNF-α, IL-1β, IL-6 and IFN-γ, all of which have been involved in cardiac hypertrophy." (PMID 29433438, 2018). "Our data provide evidence that cardiac fibroblast p38α is integral to ISO-induced cardiac hypertrophy and dysfunction and that this may be due to a paracrine signaling mechanism involving fibroblast secretion of the cardiomyocyte hypertrophy-inducing factor, IL-6." (PMID 29601781, 2018). "Our model is the first transgenic mouse model in which stimulation of local RAS in fibroblasts results in ventricular hypertrophy and fibrosis through S1PR1- and AT1-dependent IL-6 release from fibroblasts." (PMID 28771545, 2017). "Mechanistically, S1PR1-mediated cardiac hypertrophy is characterized by total dependence on Ang II-AT1 axis and IL-6." (PMID 28771545, 2017). "Cardiac hypertrophy-related MAPKs (e.g., p38, JNK and ERK1/2) and IL-6/MEK5/ERK5 signaling pathways were greatly activated, which resulted in the expression of pathologic hypertrophy response markers such as ANP and BNP in the heart of diabetic rats." (PMID 21792366, 2011). "Additionally, ALKBH5 mediates the demethylation of STAT3 and regulates the expression of inflammatory factors (such as IL-6 and TNF-α) by activating the JAK2/STAT3 signaling pathway, thereby affecting the progression of cardiac hypertrophy." (PMID 40290189, 2025). "IL-6 similarly impairs cardiac function by inducing negative inotropic effects and promoting cardiac hypertrophy and fibrosis." (PMID 40868877, 2025). "IL-6 enhances STAT3 phosphorylation in cultured CFs, whereas inhibiting STAT3 reduces IL6-induced collagen synthesis and reverses pressure overload-induced cardiac hypertrophy." (PMID 38495094, 2024). "Pressure overload-induced cardiac hypertrophy in mice was found to increase myocardial IL-6 and IL-1β levels, although TNFα levels were not affected." (PMID 38256155, 2024). "In addition, IL-6, which is produced by cardiomyocytes in response to hypertrophic stimuli, activates the STAT3 and MAPK signaling pathway in myocardial hypertrophy." (PMID 38158445, 2023).